RAB23 (RAB23, member RAS oncogene family)
Diseases named in the same sentence as RAB23 in open-access papers (continued):
Sharing a sentence is not in itself a finding about the gene and the disease.
glioma (1 paper, 2022). A benign or malignant brain and spinal cord tumor that arises from glial cells (astrocytes, oligodendrocytes, ependymal cells). "This research aimed to explore the effect of Licochalcone-A (LCA) combined with Rab23 gene on the proliferation, migration, and invasion of glioma U251 cells through the Wnt/β-catenin signaling pathway." (PMID 35497928, 2022). "The glioma U251 cell line was taken as the research object, and the Rab23 overexpression plasmid was constructed." (PMID 35497928, 2022). "In this research, glioma U251 cells were deemed as the research object, and the effects on cell proliferation, migration, and invasion were explored through overexpression of Rab23 and LCA treatment." (PMID 35497928, 2022). "In addition, the overexpression of Rab23 gene can inhibit the proliferation activity of glioma cells." (PMID 35497928, 2022). "In summary, the results of this study preliminarily showed that overexpression of Rab23 and LCA can effectively inhibit the proliferation, migration, and invasion of glioma cells through the Wnt/β-catenin signaling, and promoted cell apoptosis." (PMID 35497928, 2022). "Western blot results showed that overexpression of Rab23, LCA alone, and combined treatment can downregulate β-catenin and c-myc protein levels in glioma U251 cells, which can upregulate GSK3β and Axin2 protein levels." (PMID 35497928, 2022). "The results showed that overexpression of Rab23 and LCA treatment could inhibit the proliferation, migration, and invasion ability of human glioma U251 cells." (PMID 35497928, 2022). "However, the mechanism of Rab23 gene combined with LCA in the invasion and metastasis of glioma remains to be explored." (PMID 35497928, 2022). "Therefore, the potential molecular mechanisms of the effects of overexpression of Rab23 and LCA on proliferation, migration, and invasion of glioma U251 cells were explored." (PMID 35497928, 2022). "Moreover, the inhibition effect of overexpression of Rab23 combined with LCA on proliferation, migration, and invasion of human glioma U251 cells was significantly superior to that of single treatment group." (PMID 35497928, 2022).
medulloblastoma (1 paper, 2021). A malignant, invasive embryonal neoplasm arising from the cerebellum. "Moreover, transient overexpression of miR-367 in medulloblastoma cells caused decreased RAB23 expression resulting in increased medulloblastoma cell proliferation." (PMID 33811245, 2021).
melanoma (1 paper, 2021). A malignant, usually aggressive tumor composed of atypical, neoplastic melanocytes. "The role of SFPQ in melanoma is less clear, with a single article suggesting SFPQ attenuates RAB23 expression via binding of the lncRNA, LLME23." (PMID 34218270, 2021).
retinoblastoma (1 paper, 2014). A malignant tumor that originates in the nuclear layer of the retina. "The RAB23 gene is upregulated in retinoblastomas with 6p gain and there is evidence that RAB23 may potentiate Hedgehog signaling in cancer." (PMID 24509483, 2014).
Saethre-Chotzen syndrome (1 paper, 2021). Saethre-Chotzen syndrome (SCS) is an inherited craniosynostosis syndrome characterized by unilateral or bilateral coronal synostosis, facial asymmetry, ptosis, strabismus and small ears with prominent crus, among other less common manifestations. "Genes associated with the other syndromes (e.g., Carpenter [RAB23 gene, MEGF8 gene], Apert [FGFR2 gene], Crouzon [FGFR2 gene], Pfeiffer [FGFR2 gene, FGFR1 gene], and Saethre-Chotzen syndromes [TWIST1 gene]) were analyzed by WES analysis and none of these mutations were found on the patients." (PMID 34348791, 2021).
thyroid cancer (1 paper, 2016). "In addition, there are evidences that Rab23 plays a negative regulator in some carcinogenesis, such as thyroid cancer." (PMID 26716504, 2016). "In thyroid cancer, Rab23 was downregulated compared with the benign follicular adenoma." (PMID 26716504, 2016).
tumor (25 papers, 2012 to 2024). "Rab23 is implicated as a metastatic or tumorigenic biomarker as it shows differential expression in tumor cells and has been demonstrated to mediate proliferation and invasiveness in tumor cells." (PMID 29270202, 2017). "Signifying their capacity to restrain tumor cell progression and invasion via the modulation of RAB23." (PMID 39449798, 2024). "Overall, our study indicate that reducing Rab23 gene expression inhibit tumor cell growth and promoted apoptosis in vivo by downregulating the SHH signaling pathway." (PMID 37884351, 2024). "Both Rab23 gene and SHH pathway have also been implicated in tumor invasion and migration of HCC through their regulation of cell growth." (PMID 37884351, 2024). "Contemporary studies have unveiled a down-regulation of miR-16 and miR-665 in OS cell lines (MG63, U2OS) and OS specimens, signifying their capacity to restrain tumor cell progression and invasion via the modulation of RAB23." (PMID 39449798, 2024). "H&E staining also indicated that tumor cells in the Rab23 knockout group had significantly reduced irregularly shaped tumor cell nucleosomes, incomplete cytoplasmic membranes, and heterogeneous chromatin structures compared to the control group." (PMID 37884351, 2024). "Subcutaneous tumorigenic assays in mice showed that intraperitoneal injection of cisplatin alone or knockdown of RAB23 resulted in significantly lower tumor weight and volume compared to control mice." (PMID 37935937, 2023). "We found that miR-367-3p acts as a tumor suppressor in BCa cells, and we also identified RAB23 as its direct target." (PMID 37935937, 2023). "In thyroid cancer, the circHIPK3/miR-338-3p/RAB23 axis is shown to activate tumor cells tumorigenesis and invasiveness in vitro." (PMID 34718336, 2021). "Although more and more studies have introduced RAB23 as an oncogene in variety of human cancers, there is some evidence indicating that RAB23 plays a tumor suppressive role during carcinogenesis." (PMID 33811245, 2021). "Even though Rab23 has been mainly reported to exhibit tumorigenic activity, evidence about a function as a tumor suppressor also exists." (PMID 31426400, 2019). "In conclusion, Rab23 is a vital regulatory molecule with multiple capacity of regulating endocytic pathway, Shh signaling, tumor invasion, and metastasis, but potentially essential roles in autophagy, development, and other diseases have yet undefined." (PMID 28104793, 2017). "In biopsies of invasive SCC, expression of Rab23 greatly varied depending on the level of tumor differentiation." (PMID 26716504, 2016). "Rab23 Q68L promoted tumor formation while Rab23 S23N restrained tumor formation, compared to control (EGFP)." (PMID 26716504, 2016). "In HCC, Rab23 was found high cytoplasmic and nuclear expression, which is correlated with tumor size." (PMID 26716504, 2016). "In biopsies of invasive squamous cell carcinoma, expression of Rab23 greatly varied depending on the level of tumor differentiation." (PMID 26716504, 2016). "We observed other markedly under-expressed genes (P<0.05) included tumour-suppressor candidates that negatively regulate the Hh pathway (SUFU, GAS1, RAB23) and genes encoding inhibitory proteins (HHIP, HHAT)." (PMID 22361633, 2012). "Furthermore, in vivo studies have demonstrated that suppression of the Rab23 gene results in decreased tumor size, proliferation rate, and reduced levels of SHH‐related proteins Smoothened and GLI‐1." (PMID 37884351, 2024). "However, our results revealed a significant decrease in SMO and GLI‐1 protein levels in tumor tissues, suggesting that Rab23 plays a negative regulatory role in the SHH signaling pathway and can suppress tumor growth in HCC." (PMID 37884351, 2024). "si-RAB23 + CDDP group showed the most significant tumor suppression compared to other groups." (PMID 37935937, 2023).
tumor (continued). "miR-367-3p decreased cisplatin sensitivity of tumor cells can be somewhat reversed by down-regulation of RAB23, which may be an important target for regulating chemoresistance in BCa cells." (PMID 37935937, 2023). "However, our actual knowledge on Rab23′s role as a negative regulator of hedgehog signaling is more in line with a function as a tumor suppressor." (PMID 31426400, 2019). "Further investigation is needed to establish whether the role of Rab23 as an oncogenic protein or a tumor suppressor is cellular-dependent and the molecular mechanisms behind these regulations." (PMID 31426400, 2019). "Again, this result demonstrates Rab23 is a tumor-suppressing gene." (PMID 28104793, 2017). "Whether Rab23 acts as an oncogenic protein or a tumor suppressor is likely cellular context dependent." (PMID 28104793, 2017). "In 45 invasive SCC sections, moderately to poorly tumor differentiation and nonexposed positions is the risk factors of Rab23 positive staining." (PMID 26716504, 2016). "In cancer, Rab23 has been found to be highly expressed in carcinoma cells and is closely related to tumor cell proliferation, migration and apoptosis as an oncogene with tumor‐promoting activity, which makes it a useful cancer biomarker and potential therapeutic target." (PMID 37884351, 2024). "To further validate the suppressive influence of Rab23 on tumorigenesis in vivo, we implanted Rab23 knockout HCCLM3 cells into nude mice and examined the enlargement of tumor cells." (PMID 37884351, 2024). "High cytoplasmic and nuclear expression of Rab23 is found in 53.5 and 72% HCC patients respectively, which correlated with tumor size." (PMID 28104793, 2017). "In summary, miR-200b low ISH staining was seen in 90% (9/10) tumor samples, while positive rates for RAB21, RAB23, RAB18 and RAB3B IHC staining were 80%, 80%, 90%, 100% respectively." (PMID 24447584, 2014). "Compared with normal breast tissue, miR-200b expression was down-regulated in tumor tissue, while the contrary situations were found for RAB21, RAB23, RAB18 and RAB3B IHC staining." (PMID 24447584, 2014). "We also found six tumor related genes, TUSC2, TP53I3, TSSC4, RAB23, RAB39A, and ERG, which function as either tumor suppressor genes or oncogenes." (PMID 24007313, 2013). "With regard to cutaneous squamous cell carcinoma, our research group found that the expression level of Rab23 is higher in moderately to poorly tumor differentiation tissue and non-exposed sites." (PMID 28104793, 2017). "We found that the RAB23 played a negative role across cancers and had a high score in activating the EMT pathway, which might enhance the invasiveness of tumor cells and generate circulating tumor cells." (PMID 34824999, 2021).
cancer (20 papers, 2013 to 2025). A tumor composed of atypical neoplastic, often pleomorphic cells that invade other tissues. "Previous research has linked aberrant expression of HS3ST3A1, AQP9, MYLK, and RAB23 to cancer formation, invasion, and prognosis." (PMID 36199571, 2022). "The lower expression of IHH, BOC, RAB23, miR-195-5p, and miR-6738-3p was significantly associated with more advanced cancer stage." (PMID 33811245, 2021). "Another Rab GTPase, called Rab23, is important during mouse development, and it has been associated with several types of cancer." (PMID 31035701, 2019). "Also, the expression of RAB23 was significantly associated with more advanced cancer stage and H. pylori infection." (PMID 33811245, 2021). "Moreover, genetic null mutation or trafficking disorders of Rab23 can lead to human diseases including carpenter syndrome (CS), malignant tumor, susceptible to pathogen infection, and other related diseases." (PMID 28104793, 2017). "Overexpression of Rab23 not only is found in precancerous lesion like atrophic gastritis with intestinal metaplasia and actinic keratosis, but also has been implicated in several human cancers." (PMID 28104793, 2017). "Over the past few years, it has been confirmed by several studies that Rab23 is an oncogene that plays a critical role in promoting cancer development." (PMID 37884351, 2024). "The findings demonstrated that Rab23 knockdown suppressed the growth of cancer cells and increased apoptosis in vivo." (PMID 37884351, 2024). "RAB23 expression in normal and cancer tissues was under the influence of genetic and epigenetic factors." (PMID 37935937, 2023). "In summary, our data demonstrated for the first time that miR-367-3p functions as a cancer suppressor in UBC by downregulating the tumor oncogene RAB23." (PMID 37935937, 2023). "Studies found that overexpression of Rab23 can inhibit the proliferation activity of cancer cells and promoted cell apoptosis." (PMID 35497928, 2022). "RAB23 is recognized as a negative regulator of the Shh signaling pathway, and also as the target of many proteins involved in cancer development." (PMID 33811245, 2021). "Recently, the roles of several members of the Rab family in human cancer have drawn great attention, including Rab23 and Rab25." (PMID 26070933, 2015). "RAB23 has become a promising anti-cancer therapeutic target given the fact that it might function as an oncogene and its high expression in a variety of cancer cells." (PMID 37935937, 2023). "Furthermore, circHIPK3 sponges miR-338-3p and enhance RAB23 expression in TC cells, promoting cancer invasiveness." (PMID 36230649, 2022). "In further support of its role in signaling cascades, Rab23 is also involved in primary cilium transport, suggesting that its role in cancer could be related with signaling from the cilia." (PMID 31426400, 2019). "Changes in Rab23 levels in normal and cancer tissues could be regulated by both genetic and epigenetic factors." (PMID 28104793, 2017). "Therefore, it is speculated that DSCAM-AS1 activates the expression of RAB23 protein through miR-338-3p, thereby enhancing the interaction between cell membrane and the outside world and promoting the development of cancer cells." (PMID 38605206, 2024). "However, more researches are in desperate need of clarifying the downregulation effects of RAB23 by miR-367-3p on cell proliferation, invasion, and anticancer drug resistance in other cancer cell lines aiming to fully illuminate the role of RAB23 in tumorigenesis." (PMID 37935937, 2023). "Also altered expression of Rab23 has been reported in different types of cancers." (PMID 31426400, 2019). "In pan-cancer analysis, SHOX2 expression positive correlated with CDKN2C (R = 0.41), COL6A1 (R = 0.35), COL6A2 (R = 0.37), DCHS1 (R = 0.37), MAPK7 (R = 0.34), PRRX1 (R = 0.37), RAB23 (R = 0.36) and RSRC1 (R = 0.36) via GEPIA2." (PMID 37170390, 2023).
cancer (continued). "Moreover, Rab23 was found absent in normal astrocytes, while it was expressed in almost 50% of astrocytoma-affected patients, showing a correlation with a higher stage of cancer progression." (PMID 31035701, 2019).
infection (2 papers, 2016 to 2017). The state of being infected such as from the introduction of a foreign agent such as serum, vaccine, antigenic substance or organism. "Rab22 and Rab23 are specific to early endosomes/phagosomes and, after 1 h post-infection (p.i.), the recruitment to Mtb phagosomes decreases to 10%, indicating maturation of the compartment." (PMID 27005665, 2016). "After 10 min of infection, Rab34 and Rab5 are recruited in high percentage (~85%) whereas Rab22 and Rab23 in low percentage (~30%)." (PMID 27005665, 2016). "In addition, Rab23 may play joint roles in autophagosome formation during anti-infection process against Group A streptococcus." (PMID 28104793, 2017).
heart disease (1 paper, 2024). "Congenital heart disease is present in 6/8 cases reported here, 4/7 previously reported cases of MEGF8-associated CRPTS and 10/39 previously reported cases of RAB23-associated CRPTS." (PMID 38760421, 2024).
patella (1 paper, 2023). "We show that RAB23-deficient mice fail to develop patella and that missing patella in Rab23−/− mice was not due to the programmed cell death." (PMID 36910145, 2023).
RAB23 also shares sentences with these, for which no sentence is quoted: Obesity (7 papers); Polysyndactyly (4); intellectual disabilities (2); Autoimmunity (1); brain diseases (1); breast tumor (1); colorectal adenocarcinoma (1); developmental delay (1); esophageal squamous cell carcinoma (1); focal segmental glomerulosclerosis (1); glioblastoma (1); Joubert syndrome (1); neuroblastoma (1); non-small cell lung carcinoma (1); polydactyly (1); renal cell carcinoma (1); Robinow syndrome (1); small cell lung carcinoma (1); Talipes equinovarus (1); uveitis (1); van Maldergem syndrome (1).